VIP (vasoactive intestinal peptide)
Diseases named in the same sentence as VIP in open-access papers (continued):
Sharing a sentence is not in itself a finding about the gene and the disease.
cancer (continued). "Similar to SCLC, we found that NSCLC cell proliferation was stimulated by the low dose of VIP (10 nM); cancer growth was reduced by the high concentration of VIP." (PMID 35011543, 2022). "Some of the significant cancer hallmark terms are epithelial-mesenchymal transition (MSX1, CXCL12, SCG2, SLIT2), KRAS signaling up (F13A1, ADAMDEC1), inflammatory response (CCL5, VIP), IL-6/JAK/STAT3 signaling (CXCL13)." (PMID 35486660, 2022). "Vasoactive intestinal peptide (VIP) is a neuropeptide that regulates the inflammatory response, and is involved in the pathogenesis of various cancers." (PMID 33330631, 2020). "There were also attempts to use radio-labeled VIP analogs in cancer imaging and only recently the basis of peptide analogs selectivity in the activation of PAC1 versus VPAC1 was described." (PMID 31491880, 2019). "Myeloid-derived suppressor cells (MDSC) are an immune regulatory cell type that has been described in settings of cancer and infectious disease._Here we demonstrate a reduced circulating monocytic MDSCs in the VIP -/-vs. wild type MCMV." (PMID 29137229, 2017). "A preliminary pan-cancer analysis indicated potential dysregulation of VIP pathway genes." (PMID 42216340, 2026). "Furthermore, VIPR2 has been shown to form homodimers and oligomers, which are involved in VIP-induced cancer cell migration." (PMID 39869563, 2025). "The differential expression patterns of VIP and its receptors across different histologies suggest distinct roles and potential interactions between VIP-receptor signaling and other pathways in cancer." (PMID 37444395, 2023). "More recently, it has been suggested that in cancer stem cells, VIP signalling may be a method by which cancer stem cells are resistant to therapy." (PMID 37830741, 2023). "Further studies are necessary to understand how inhibiting or activating the VIP–VPAC axis may serve as a prognostic biomarker of cancer metastasis or a predictive biomarker for response to VIP-targeted therapies on EMT in gastrointestinal malignancies." (PMID 37444395, 2023). "Comprehensive gene expression studies of cancer are valuable when studying peptides such as VIP." (PMID 37444395, 2023). "VIP affects the growth of some tumors, and VIP autocrine regulation is present in some cancers." (PMID 37771430, 2023). "Therefore, we conducted an in silico gene expression analysis to study the mechanisms of autocrine VIP signaling in cancer." (PMID 37444395, 2023). "Based on these, it is inferred that the increased expression of VIP and its receptor may be related to cancer-related inflammation." (PMID 35174205, 2022). "Thus, the salubrious effect of VIP-R antagonist treatment on anti-cancer immunity in the PDAC models is likely due to local effects of VIP in the TME where VIP is pathologically overexpressed." (PMID 36302761, 2022). "Expression of VIP by PDAC and the TME suggested that VIP may function as a paracrine and/or autocrine factor for cancer cell survival." (PMID 36302761, 2022). "VIP was shown to be involved in the promotion of cancer progression." (PMID 35011543, 2022). "Additionally, VIPR1 and VIP/VIPR1 signaling have received great attention in cancer research because of their pleiotropic roles in different types of cancer." (PMID 35864952, 2022). "NTS, BB, and VIP conjugates, which kill cancer cells, have been developed." (PMID 30008698, 2018). "Addition of VIP to cancer cells results in elevated cAMP which activates PKA." (PMID 30008698, 2018). "The role of VIP as a modulator of the number and function of MDSCs might broaden the potential clinical application of VIP inhibitors in cancer immunotherapy." (PMID 29137229, 2017). "Thus, the interruption of VIP signaling with specific antagonists represents a new therapeutic approach for the treatment of cancers." (PMID 23365656, 2013).
cancer (continued). "Receptors for peptides secreted by neuroendocrine cells, such as secretin, gastrin, bombesin, cholecystokinin, and vasoactive intestinal peptide, have been identified in many cancer types, including cancers of lung, ovarian, thyroid, brain, genitourinary and gastrointestinal tract." (PMID 24392036, 2013). "We have showed that the gastric adenocarcinoma tissues contained secreting VIP cancer cells." (PMID 24228003, 2013). "The presence of VPAC in both VIP-expressing and non-expressing tissues suggests that cancers may be simultaneously susceptible to both autocrine and paracrine VIP effects." (PMID 37444395, 2023). "Since the effects of VIP and PACAP are regulated by VIPRs, various analogs of them are used for the treatment therapies of physiological problems associated with gastrointestinal, immune, reproductive, respiratory, cardiovascular, and endocrine systems, as well as cancer malignancies." (PMID 35203615, 2022). "The VIP antagonist may be helpful antigastric cancer drug by targeted VIP." (PMID 24228003, 2013). "Most studies localize this peptide both in EECs, where colocalization with other NPs is common, e.g., chromogranin A, serotonin, glucagon, bombesin, vasoactive intestinal peptide (VIP), and in cancer cells." (PMID 38540191, 2024). "Many cancers express VIP and its surface receptors VPAC1 and VPAC2, but the role of autocrine VIP signaling in cancer as a targetable prognostic and predictive biomarker remains poorly understood." (PMID 37444395, 2023). "Healthy gastric, colon, esophageal, and pancreatic tissues had R coefficients between VIP and ZEB1, an expression similar to those seen in TCGA cancer tissues (p < 0.0001 for all analyses)." (PMID 37444395, 2023). "Inhibition of VIP and PACAP receptors is an emerging concept for new pharmacotherapies for chronic inflammation and cancer, while activation of their receptors provides neuroprotection." (PMID 35203615, 2022). "Considering the variation in expressions of VIP and PACAP receptors in both normal as well as cancer tissues during different malignant conditions, these receptors have gained a lot of attention also as a molecular signature for targeted imaging." (PMID 35203615, 2022). "From our best research, HOXC6, SLC2A4, VIP, CD1A, STC2, and OLFM2 are related to cancer progression." (PMID 35711425, 2022). "VIP and PACAP receptors have been identified as potential therapeutic targets for the treatment of chronic inflammation, neurodegenerative diseases and cancer." (PMID 34867774, 2021). "VIP/PACAP, together with their receptors (VPAC1, VPAC2/PAC1), can also promote growth and proliferation of normal and cancer cells." (PMID 32429087, 2020). "A recent study comprehensively investigated the cytoprotective effects of the small neuropeptide VIP and its receptor (VIPR1) in cancer stem cells and identified an antiapoptotic function of the VIP receptor in these cancer cells." (PMID 31363108, 2019). "The review will focus on how BB, NTS, VIP, and SST receptors can facilitate the early detection and treatment of cancer." (PMID 30008698, 2018). "VPAC1 has been used to deliver VIP analogs containing cytotoxic CPT, paclitaxel, ellipticin or geldanomycin to cancer cells." (PMID 30008698, 2018). "Despite the growth and spread of tumors in both VIP KO and C57BL/6 groups injected with cancer cells, only VIP KO mice died prior to the end of the study." (PMID 28824540, 2017). "The growth and spread of the cancer was measured over a period of 4 weeks in C57BL/6 mice and 5 weeks in VIP knockout (KO) mice." (PMID 28824540, 2017). "Taken together, the VIP–VPAC axis offers a widely expressed and targetable biomarker in cancer." (PMID 37444395, 2023). "VIP-immunoreactivity occurs in a number of tumors, and VIPR1 is overexpressed, resulting in high densities, in numerous cancers including bladder, breast, colon, lung, pancreatic, and prostate cancers, although there are some inconsistencies with other studies." (PMID 36237322, 2022).
cancer (continued). "Interhelical interactions in VIP and PACAP receptors that are important for agonist binding and/or activation provide a molecular basis for the design of novel selective drugs demonstrating anti-inflammatory, anti-cancer, and neuroprotective effects." (PMID 35203615, 2022). "The Kaplan–Meier analysis further suggests that the lack of endogenous VIP production significantly increases the likelihood of death to cancer." (PMID 28824540, 2017). "VIP binds to VIPR and performs a wide variety of functions in cancer and normal cells." (PMID 28569785, 2017). "Interestingly, there were no significant quantitative differences in the numbers of SP+, SM+, Vasoactive Intestinal Polypeptide (VIP)-ergic and Pituitary Adenylate Cyclase-activating Peptide (PACAP)-ergic neurons, as well as SM+ nerve fibers in cancer, compared with healthy regions." (PMID 32429087, 2020). "Neither VIP KO controls nor WT controls developed or succumbed to cancer." (PMID 28824540, 2017). "As VIPR are abundantly expressed in cancer cells as well as tumors, and no information is available on the cytoprotective efficacy of VIP in CSCs, we tested whether VIP protects CSCs from apoptosis." (PMID 28569785, 2017). "Furthermore, overexpression of VIP may represent a biomarker useful to identify patients with PDAC and other cancers sensitive to the ICB activity of VIP-R antagonists, analogous to the use of PD-L1 staining of cancer as a predictive biomarker for response to anti-PD1 ICB." (PMID 36302761, 2022). "An increased level of VIP/PACAP and their receptors in cancer and variation of their levels observed during cancer progression makes it the best candidate not just for detection of different cancers but also for their diagnosis." (PMID 35203615, 2022).
infection (24 papers, 2012 to 2025). The state of being infected such as from the introduction of a foreign agent such as serum, vaccine, antigenic substance or organism. "Our data show that SARS-CoV-2 enterocyte infection causes ER stress and the release of DAMPs, both of which increase the expression and release of VIP by EN." (PMID 36830577, 2023). "The protective action of VIP occurs by inhibition of damaging NO-generation caused by the infection, both indirectly via cytokines and directly via pathogens." (PMID 30252907, 2018). "C. rodentium infection caused a gradual decline in VIP staining with maximum loss of VIP on day 10 and 14 post-infection, featuring marked reduction in immunoreactivity especially in the mucosal and submucosal region (p<0.001)." (PMID 30252907, 2018). "Functionally, these dual mechanisms of VIP-mediated downregulation of proteins involved in SARS-CoV-2 cell entry resulted in a reduced infection rate by the SARS-CoV-2 pseudovirus." (PMID 40141308, 2025). "Especially in combination with reducing the surface expression of ACE2 and TMPRSS2 and the reduction of the activity of TMPRSS2, the infection of the cell is impaired by VIP." (PMID 40141308, 2025). "failed to efficiently colonize the lungs and clear more rapidly the infection from the lungs, suggesting that Bordetella harbor mechanisms to manipulate VIP/VPAC2 signaling." (PMID 37065208, 2023). "After infection with S. agalactiae, the expression of On-VIP increased following a time-dependent pattern in brain, head kidney, and intestine." (PMID 36499231, 2022). "The analysis showed that although there are starter cells in L2-6 at both time points we get robust primary infection in L2/3 for both VIP+ and SST+ cells." (PMID 33184269, 2020). "Other types of AMPs like Urocortin II and Vasoactive Intestinal peptide (VIP) analogs, were capable of controlling infection in the cutaneous form of the disease in Balb/c mice." (PMID 30811391, 2019). "This suggests that VIP levels, similarly to mitochondrial function, may be more affected by the cytokine environment than pathogen density, as we previously have shown that the C. rodentium density is similar between WT and IFNγ deficient infected mice at day 10 post infection." (PMID 30252907, 2018). "Next, we investigated if the decrease of enzyme activity of mitochondrial complexes on day 10 and 14 post infection in mice was alleviated by treatment with VIP (0.5 nmol/ mouse/ day)." (PMID 30252907, 2018). "Together with our data where treatment started day 10 post infection to mimic therapeutic treatment, this suggests that the timing of the VIP treatment is important." (PMID 30252907, 2018). "Thus, our results suggest that disruption of VIP/VPAC2 signaling axis promotes clearance the infection from the lungs." (PMID 37065208, 2023). "Our previous results revealed that using B. bronchiseptica in this study could provide a more mechanistic understanding of the role of VIP/VPAC2 signaling in the infection dynamics." (PMID 37065208, 2023). "utilize VIP/VPAC axis to promote intracellular survival in macrophages, suggesting that VIP/VPAC axis might influence infection dynamics and persistence." (PMID 37065208, 2023). "However, the expression levels of On-VIP were remarkably increased in the brain at 24 h after infection." (PMID 36499231, 2022). "Here we utilized an in vivo-like in vitro human colonic mucosal surface with a three-dimensional architecture, functional tight junctions, polarized cells and mucus secretion, to investigate the relation between VIP, these cytokines, infection and mitochondrial function." (PMID 30252907, 2018). "On one hand, if VIP can protect the mitochondrial function during infection, it may enhance the protective barrier to infection, both via protection against apoptosis and via increased mucus secretion." (PMID 30252907, 2018).
infection (continued). "VIP treatment for day 5–10 alleviated the reduction in mitochondrial phosphorylation capacity for both the day 10 (-51% to -8%, p<0.05) and day 14 (-61% to -17%, p<0.05) post infection groups." (PMID 30252907, 2018). "As a consequence, ATP generation was also hampered at day 10 and 14 post-infection (p<0.01), and VIP treatment for day 5–10 alleviated the reduction at both time points (-46% to -8%, p<0.05, and -48% to -25%, p<0.05), whereas treatment for day 10–14 or 5–14 was less effective." (PMID 30252907, 2018). "Since our results demonstrated a decrease in colonic VIP after infection, we hypothesized that restoring VIP levels may yield protection." (PMID 30252907, 2018). "The impairment of the mitochondrial phosphorylation caused by infection and cytokines was relieved by VIP to a level similar to that of non-treated mucosal membranes (p<0.01)." (PMID 30252907, 2018). "Of note, increased VEGF expression seen in WT BL/6 mice after mCMV infection but not in VIPhyb-treated or VIP-KO mice has been also associated with decreased DC maturation and VIP-signaling." (PMID 23723978, 2013). "Moreover, the results for the cAMP-PKA pathway were evaluated through in vivo infection and were consistent with those obtained through in vitro infection, suggesting that the immune regulation mechanisms of VIP may be conservative in Nile tilapia." (PMID 36499231, 2022). "On the other hand, as VIP has anti-inflammatory properties, this may impede the pathogen clearance as it has been demonstrated that for example IFNγ plays a role during clearance of infection." (PMID 30252907, 2018). "Similarly, the mitochondrial transmembrane potential was reduced by 50% or more at both day 10 and 14 post infection (p<0.001), and VIP treatment for day 5–10 alleviated the reduction at both time points (p<0.05), whereas treatment for day 10–14 or 5–14 was less effective." (PMID 30252907, 2018). "That VIP is protective in vitro, suggests that the decreased levels of VIP occurring in the colonic epithelial cells during infection may lead to that the infection induced expression of TNFα and IFNγ inflict even greater damage than what might have occurred otherwise." (PMID 30252907, 2018). "Epithelial cells (CaCo-2) were stimulated with SARS-CoV-2 spike protein, treated with native VIP and analyzed to investigate the mRNA and surface expression of ACE2 and TMPRSS2, the enzyme activity of TMPRSS2 and the infection rate by a SARS-CoV-2 pseudovirus." (PMID 40141308, 2025). "in combination with different mouse strains we were able to evaluate the role of VIP/VPAC2 signaling in the infectious dose 50 and infection dynamics." (PMID 37065208, 2023). "Compared with the normal control group, infection by ETEC K88 significantly increased serum TNF-α, IL-6, IL-1β, IFN-γ, VIP, sIgA and histamine levels, as well as the β-hexosaminidase, tryptase and MPO activities." (PMID 34899686, 2021). "We observed that VIP and PACAP promoted CREB phosphorylation in uninfected as well as in HIV-1-infected macrophages (7 days of infection)." (PMID 29951068, 2018). "We found that pre-exposure to VIP and PACAP (10 nM) resulted in long-term inhibition of HIV-1 replication, albeit to a lesser extent compared to post-infection treatment." (PMID 29951068, 2018). "Enhanced numbers of IFN-γ+ and TNF-α+ expressing NK and NK T-cells were seen in VIPhyb-treated WT and VIP-KO mice, with peak numbers of IFN-γ+ NK cells and TNF-α+ NK cells seen 40 hours after mCMV infection, compared with PBS-treated WT mice." (PMID 23723978, 2013). "VIP can bind to VIP receptor 2 (VPAC2) on the surface of ILC2s, thus promoting ILC2s to secrete IL-5, which can recruit eosinophils, participate in infection and immune response, and sensory neurons can secrete vasoactive intestinal peptide under IL-5 stimulation." (PMID 34659628, 2021). "Furthermore, VIP-SPOT results also correlated with plasma viral load (r = 0.73; P = 0.001) in untreated infection." (PMID 34154408, 2021).